RN7SL77P (RNA, 7SL, cytoplasmic 77, pseudogene)
Gene: Miscellaneous RNA gene on chromosome 14 (70,610,086 to 70,610,379, forward strand). Ensembl gene ENSG00000240837.
Homologues: Orthologues: chimpanzee Metazoa_SRP (99% identical), macaque Metazoa_SRP (93% identical). Paralogues in human: RN7SL1 (82% identical), RN7SL296P (82% identical), RN7SL2 (82% identical), RN7SL3 (82% identical), RN7SL397P (79% identical), RN7SL566P (79% identical), RN7SL126P (79% identical), RN7SL220P (79% identical), RN7SL478P (79% identical), RN7SL679P (79% identical), RN7SL712P (79% identical), RN7SL788P (79% identical), and 702 more.